CRHR1 (corticotropin releasing hormone receptor 1)
Diseases named in the same sentence as CRHR1 in open-access papers (continued):
Sharing a sentence is not in itself a finding about the gene and the disease.
colon cancer (3 papers, 2021 to 2024). "In conclusion, our data clearly suggest that the Crhr1 deficiency confers a tumor-suppressing effect, while the Crhr2 deficiency has the potential to worsen the development and growth of colon cancer." (PMID 33494263, 2021). "We found that the mRNA level of CRHR2 was substantially lower in colon cancer tissues than that of normal tissues, while the CRHR1 levels are comparable between these tissues." (PMID 33494263, 2021). "Together, these data suggest that in the mouse model of AOM/DSS-induced colon cancer, Crhr2 deficiency exacerbates tumorigenicity, while loss of Crhr1 does not seem to alter the intestinal tumor development and growth." (PMID 33494263, 2021). "Therefore, either antagonists against CRHR1 or pharmacological activation of CRHR2-mediated responses should merit further investigation for developing a novel approach against colon cancer in humans." (PMID 33494263, 2021). "Furthermore, to access the role of CRHR-mediated responses in colon cancer, we tested Crhr1−/− mice and Crhr2−/− mice in two different animal models of human colon cancer: the Apcmin/+ mouse model and the AOM/DSS-treated model." (PMID 33494263, 2021). "Therefore, pharmacological inhibitors of CRHR1 or activators of CRHR2 could be of significance as anti-colon cancer drugs." (PMID 33494263, 2021). "However, we could not observe this tumor-suppressing effect of Crhr1 deficiency in the AOM/DSS model of colon cancer." (PMID 33494263, 2021). "Thus, we investigate the role of CRHR1 and CRHR2 in colon cancer." (PMID 33494263, 2021). "Furthermore, the mRNA level of UCN III, a CRHR2-specific peptide among the CRH family, was dramatically reduced in colon cancer tissues compared to that of controls; however, the level of CRH, a CRHR1-restricted ligand, was not changed in these tissues." (PMID 33494263, 2021).
dependence (3 papers, 2018 to 2025). "Finally, while preclinical evidence consistently implicates CRHR1 in stress- and dependence-driven alcohol behaviors, clinical translation has so far been unsuccessful: CRHR1 antagonists such as pexacerfont and verucerfont have failed to attenuate craving or relapse in human trials." (PMID 41181610, 2025).
diabetes mellitus (3 papers, 2021 to 2025). A metabolic disorder characterized by abnormally high blood sugar levels due to diminished production of insulin or insulin resistance/desensitization. "When CRHR1 and the GHRH receptor are activated in pancreatic islets, they stimulate insulin synthesis and alter glucocorticoid balance, which may contribute to the development of diabetes mellitus." (PMID 41294018, 2025).
Infertility (3 papers, 2012 to 2023). "Nonetheless, fetal Leydig cell function has not been analyzed rigorously in Crhr1 knockout mice, and it remains possible that fetal Leydig cell steroidogenesis is reduced in these mice but not to a level that would cause masculinization defects resulting in infertility." (PMID 23133512, 2012). "Our findings point to a new inflammatory modulator pathway in which CRH, UCN, CRHR1 and CRHR2 are involved acting by an autocrine/paracrine pathway in eutopic and ectopic endometrium potentially affecting the pathogenesis of this benign disease and infertility profile of endometriotic women." (PMID 23638035, 2013).
insomnia (3 papers, 2019 to 2021). A sleep disorder characterized by difficulty in falling asleep and/or remaining asleep. "This research program can hopefully prove that the vibrating belly and ring kneading method can treat insomnia through modulating the CRH/CRHR1 pathway of brain–gut interaction, and thereby verify the correctness of the brain–gut interaction theory." (PMID 34106630, 2021). "Based on the theory of brain–gut interaction in the treatment of insomnia with abdominal massage, this study will further analyze the possible relationship between hypothalamus and brain–gut axis, CRH/CRHR1 pathway and sleep, and between HPA axis and sleep." (PMID 34106630, 2021). "SNPs rs117615688 in CRHR1 and rs382940 in SLC44A1 are associated the non-motor symptoms of insomnia and restless leg syndrome (RLS), respectively." (PMID 33935957, 2021).
memory impairment (3 papers, 2016 to 2021). "We sought to investigate that the roles of CRHR1 and CXCL5 in learning and memory impairment caused by prenatal sGC exposure." (PMID 33810797, 2021).
substance abuse (3 papers, 2018 to 2025). The use of a drug for a reason other than which it was intended or in a manner or in quantities other than directed. "Hippocampal CRH secretion is known to contribute to stress-induced substance abuse and increased activation of pyramidal target neurons via CRHR1, which tend to produce anxiogenic effects." (PMID 29379100, 2018).
Cerebral ischemia (2 papers, 2018 to 2019). Restriction of arterial blood supply to the brain associated with insufficient oxygenation to support the metabolic requirements of the tissue. "A recent study using intracerebroventricular administration of antalarmin showed that blocking CRHR1 provides neuroprotection and blunts neuroinflammation resulting from global cerebral ischemia." (PMID 30427841, 2018).
idiopathic fibrosing alveolitis (2 papers, 2021 to 2022). "Among 67 respiratory conditions tested, 11 had significant associations including MUC5B locus (rs35705950) with increased risk of idiopathic fibrosing alveolitis OR 2.83, p=4.12 × 10−191; CRHR1 (rs61667602) associated with reduced risk of pulmonary fibrosis, OR 0.84, p=2.26 × 10−12." (PMID 34642702, 2021).
melanoma (2 papers, 2023). A malignant, usually aggressive tumor composed of atypical, neoplastic melanocytes. "Then, we identified 9 LR pairs (“BMP6- > HJV” 、"CCL8- > ACKR4” 、"DLL3- > NOTCH3"、"DSC3- > DSG3"、"GHRH- > GHRHR” 、"LRRC4B- > PTPRF"、"SEMA4D- > PLXNB1"、"SFRP1- > FZD6"、"UCN- > CRHR1′′) as key LR pairs in melanoma prognosis through Lasso Cox regression and Multiple Stepwise Regression." (PMID 36777724, 2023).
neuroblastoma (2 papers, 2023 to 2024). Neuroblastoma (NB) is the most common solid, extracranial childhood tumor. "Activation of CRHR1 by CRH has been shown to increase the release of APP in rat cerebellar neurons, in human neuroblastoma IMR32 cell line, and in mouse hippocampal HT22 cells." (PMID 38706793, 2024).
pulmonary fibrosis (2 papers, 2021 to 2022). Chronic progressive interstitial lung disorder characterized by the replacement of the lung tissue by connective tissue, leading to progressive dyspnea, respiratory failure, or right heart failure. "Among the respiratory conditions, only idiopathic pulmonary fibrosis (IPF) and chronic alveoli lung disease had shared associations with the variants near genes MUC5B, CRHR1, and NSF." (PMID 35482673, 2022). "Among the respiratory conditions, only idiopathic pulmonary fibrosis (IPF) and chronic alveoli lung disease had associations with the variants near genes MUC5B, CRHR1, and NSF." (PMID 34642702, 2021).
Sepsis (2 papers, 2015 to 2021). Sepsis is defined as life-threatening organ dysfunction caused by a dysregulated host response to infection. "Notably, our studies demonstrated that inhibiting CRH from binding its target receptor CRHR1 caused increased pneumonia and sepsis." (PMID 25904910, 2015).
airway hyperresponsiveness (1 paper, 2022). "A polymorphism of the corticotropin-releasing hormone receptor 1 (CRHR1) has been related to improved lung function during ICS treatment, instead, polymorphisms in the TBX21 gene are likely to be associated to an improvement in airway hyperresponsiveness." (PMID 35327702, 2022).
behavioral disorders (1 paper, 2020). "Our findings highlight that dysregulation of CRHR1-BDNF signaling in BNST underlies, at least in part, ELS-related maladaptive affective aspects of behavioral disorders." (PMID 33177511, 2020).
cerebral edema (1 paper, 2016). "Systemic inflammation can facilitate onset of hypoxic cerebral edema through interaction of astrocyte and microglia by activation of TLR4 and CRH/CRHR1 signaling." (PMID 26968975, 2016).
colorectal tumors (1 paper, 2017). "Further, CRHR1-KANSL1 fusions have been reported in 5% of TCGA's colorectal tumors and 3.5% of TCGA's uterine carcinosarcomas." (PMID 28423358, 2017). "CRHR1-KANSL1 fusions were reported in 5% of TCGA's colorectal tumors (16 of 312 analyzed), and 3.5% of TCGA's uterine carcinosarcomas (2 of 57 analyzed)." (PMID 28423358, 2017).
contact dermatitis (1 paper, 2012). An inflammatory skin condition caused by direct contact between the skin and either an irritating substance or an allergen. "CRHR antagonists (e.g., antalarmin or astressin) would be one class of molecules that could be tested by local administration in the model systems described, especially because higher CRHR-1 gene expression was documented in contact dermatitis." (PMID 21977335, 2012).
developmental delay (1 paper, 2012). "We find increased expression of CRHR1 associated with H2 configuration, suggesting that CRHR1 activity and/or stress response might also be altered in or contributing to the H2 related phenotypes such as developmental delay and learning disability." (PMID 22950410, 2012).
edema (1 paper, 2016). An abnormal accumulation of fluid beneath the skin, or in one or more cavities of the body. "We have recently reported that in rats, hypoxia-induced overactivation of CRHR1 and AQP4 produces cerebral edema tested by magnetic resonance imaging (MRI)." (PMID 26968975, 2016).
glucocorticoid deficiency (1 paper, 2020). "CRF1 knockout mice (Crhr1-/-) are known to display chronic glucocorticoid deficiency as a result of interference with the HPA axis." (PMID 32244319, 2020).
hyperadrenocorticism (1 paper, 2017). "The present study aimed to investigate mutations in the CRHR1 coding region in poodles with pituitary-dependent hyperadrenocorticism." (PMID 29069262, 2017).
infantile spasms (1 paper, 2015). A rare epilepsy syndrome characterized by onset of epileptic spasms in infants between 2 and 12 months of age, and rarely up to 24 months. "It was the first attempt to study the impact of polymorphisms in the CRHR1 gene in Chinese individuals with infantile spasms." (PMID 25954915, 2015). "In spite of the strong rationale of the present study, the case-control results did not reveal any statistically significant associations between polymorphisms in the CRHR1 gene and infantile spasms." (PMID 25954915, 2015). "In the present study, CRHR1 was selected as a candidate gene to investigate its association with the risk of infantile spasms and the effectiveness of ACTH treatment." (PMID 25954915, 2015). "In the present study, the CRHR1 gene was analyzed as a candidate to test its association with the onset of infantile spasms, as well as its responsiveness to ACTH treatment." (PMID 25954915, 2015). "In conclusion, the present study presented a preliminary evaluation of the role of variations in the CRHR1 gene in infantile spasms." (PMID 25954915, 2015). "In order to detect the effect of rare variations in the CRHR1 gene using a case control methodology, a significantly larger number of infantile spasms and control individuals would be required to be analyzed." (PMID 25954915, 2015). "Alternatively, it may be possible to identify rare but important variations in the CRHR1 gene by directly sequencing regions of the CRHR1 gene in a smaller sample of infantile spasms and control individuals." (PMID 25954915, 2015). "However, whether genetic variants of CRHR1 are associated with infantile spasms, has not been studied in depth." (PMID 25954915, 2015). "It is, however, possible that rare variants in the CRHR1 gene may have a role in the onset of infantile spasms and the effect of such polymorphisms may not have been detected in the relatively small population of infantile spasm cases enrolled in the present study." (PMID 25954915, 2015). "The present study hypothesized that CRHR1 is involved in the development of infantile spasms, and to the best of our knowledge, no studies have been conducted regarding the association between the polymorphisms of CRHR1 and infantile spasms to date." (PMID 25954915, 2015).
intrauterine growth restriction (1 paper, 2022). "The treatment of BeWo cells with exogenous CRH results in the elevation of cellular corticotropin releasing hormone receptor 1 (CRHR1) levels, which are significantly reduced in PE and intrauterine growth restriction (IUGR)." (PMID 36187484, 2022).
ischemia (1 paper, 2025). A hypoperfusion of the BLOOD through an organ or tissue caused by a PATHOLOGIC CONSTRICTION or obstruction of its BLOOD VESSELS, or an absence of BLOOD CIRCULATION. "Namely, the peptide reduced the expression of many genes (e.g., P2rx6, Gabra3, Grik4, Oprl1, Glra2, Crhr1, Hrh1, Chrm5, Grik1) related to the neurosignaling system and whose expression was not significantly changed by ischemia itself." (PMID 40650034, 2025).
lichen (1 paper, 2024). "Expression of the receptor CRHR1 was studied in 31, 27 and 29 cases of lichen, VIN and VSCC, respectively." (PMID 37382757, 2024). "In the present retrospective study, we investigated the immunohistochemical expression of CRH, UCN, FAS-L and of their receptors CRHR1, CRHR2 and FAS, on paraffin-embedded tissue samples from patients diagnosed with lichen (sclerosus or planus), VIN or VSCC." (PMID 37382757, 2024). "Immunohistochemical expression of CRH, urocortin (UCN), FasL and their receptors CRHR1, CRHR2 and Fas was studied in vulvar tissue sections obtained from patients with histologically confirmed diagnosis of lichen, vulvar intraepithelial neoplasia (VIN) and vulvar squamous cell carcinoma (VSCC)." (PMID 37382757, 2024).
multiple sclerosis (1 paper, 2012). A progressive autoimmune disorder affecting the central nervous system resulting in demyelination. "In addition, multiple sclerosis (MS) has been associated to HPA-axis activity, specifically genetic variants in CRHR1." (PMID 22950410, 2012).
necrotizing enterocolitis (1 paper, 2017). Necrotizing enterocolitis (NEC) is a devastating disease that affects mostly the intestine of premature infants. "Thus, selectively blocking CRHR1 and promoting CRHR2 activity could prevent the development of intestinal injuries and enhance repair in the neonatal period when there is increased risk of intestinal injury such as necrotizing enterocolitis." (PMID 28492284, 2017).
ovarian tumour (1 paper, 2007). "Since a large proportion of ovarian tumours were found to express CRHR1 (70.2%), secretion of CRH might considerably improve tumour's resistance to immune attack and thus favour its survival and progression." (PMID 17667919, 2007). "In summary, we found that CRH, its receptors CRHR1 and CRHR2, and the proapoptotic molecule FasL are produced by human ovarian tumour cells in situ." (PMID 17667919, 2007).
pneumococcal infection (1 paper, 2017). Infections with bacteria of the species streptococcus pneumoniae. "Interestingly, intranasal administration of antalarmin significantly reduced the protective effect of CRH, suggesting that endogenous ligation of CRH to its cognate receptor CRHR1 could be mediating responses during pneumococcal infection." (PMID 28057851, 2017).
skin cancer (1 paper, 2025). "Given the existence of several CRHR1 isoforms with distinct functional roles, this may underestimate the complexity of CRHR1-mediated effects in skin cancer." (PMID 40917468, 2025).
Sleep disturbance (1 paper, 2024). An abnormal pattern in the quality, quantity, or characteristics of sleep. "(b) FKBP5 rs1360780-T and rs4713916-A alleles and the CRHR1 rs110402-G allele were associated with the risk of sleep disturbances." (PMID 38525273, 2024). "The FKBP5 rs1360780-T and rs4713916-A alleles and the CRHR1 rs110402-G allele were risk factors for sleep disturbances, with adjusted ORs (95% CIs) of 1.75 [1.38–2.22], 1.68 [1.30–2.18] and 1.43 [1.09–1.87], respectively (all P = 0.001, Bonferroni-corrected P < 0.01)." (PMID 38525273, 2024).
somatotropinoma (1 paper, 2018). "In contrast, other receptors subtypes involved in the function of different pituitary cell types, such as gonadotropin-releasing hormone receptor (GnRHR), corticotropin-releasing hormone receptor (CRHR1) or vasopressin receptor (AVPR1b) were not noticeably expressed in somatotropinoma samples." (PMID 29670116, 2018).
Stroke (1 paper, 2012). Sudden impairment of blood flow to a part of the brain due to occlusion or rupture of an artery to the brain. "Crhr1 and Crhbp were either transiently or persistently downregulated both in young and aged rats in response to stroke and, more importantly, their expression did not recover by day14 post-stroke, remaining especially low in aged animals." (PMID 23251410, 2012).
uterine tumor (1 paper, 2017). "CRHR1 has also been reported fused with CENPP, KIA0100, and SPOP, in one breast, cervical, and uterine tumor, respectively." (PMID 28423358, 2017).
psychiatric disorder (14 papers, 2012 to 2025). A disorder characterized by behavioral and/or psychological abnormalities, often accompanied by physical symptoms. "As in the case of the CRHR1 gene, it has been shown that childhood trauma exposes individuals possessing rs3800373 to an increased risk of developing mental illnesses in adulthood." (PMID 40869374, 2025). "Involvement of CRHR1 genotype in the present study might be explained by its association with mental health disease." (PMID 31959877, 2020). "Numerous studies have associated abnormalities in the functioning of the hypothalamic–pituitary–adrenal (HPA) axis with mental disorders, correlating in this context, the involvement of the CRHR1 and FKBP5 genes in inducing suicide behaviors." (PMID 40869374, 2025). "The maximum difference in mean CRHR1 methylation between the subgroups was more than 3%, a change comparable to or even larger than other studies examining peripheral blood DNA methylation and psychiatric disorders or psychiatric treatment response." (PMID 30390684, 2018).